CRP (C-reactive protein)
Diseases named in the same sentence as CRP in open-access papers (continued):
Sharing a sentence is not in itself a finding about the gene and the disease.
Multiple Organ Failure (25 papers, 2014 to 2025). A progressive condition usually characterized by combined failure of several organs such as the lungs, liver, kidney, along with some clotting mechanisms, usually postinjury or postoperative. "Increased circulating CRP levels correlate with an increased risk of multiple organ failure and death." (PMID 36289811, 2022). "Among other limitations noted during the interpretation of the results, it is important to mention the lack of complete data collected in the preliminary stage regarding CRP, PCT, and the parameters of multiple organ failure, which precluded the incorporation of the SOFA scale into the study." (PMID 40004075, 2025). "It is difficult to speculate on the course of AGEs during acute critical illness, because the relationship between CRP and AGEs may change during the course of the disease and we did not document the course of AGEs prior to developing multiple organ failure." (PMID 27529340, 2016).
Myocardial fibrosis (25 papers, 2013 to 2025). "Elevated CRP levels have been shown to contribute to myocardial fibrosis, cardiac remodeling, and impaired pump function." (PMID 41393266, 2025). "Patients with LVDD exhibited the highest levels of TNF-α and CRP, aligning with prior findings that link systemic inflammation to myocardial fibrosis and diastolic dysfunction." (PMID 39727643, 2024). "A recent study suggested that CRP not only is an inflammatory marker, but also promotes inflammation and subsequent myocardial fibrosis through the TLR4/NF-κB/TGF-β pathway." (PMID 36855116, 2023). "A previous investigation proposed that CRP functions not only as an indicator of inflammation but also as a promoter of inflammation, thereby leading to myocardial fibrosis through the TLR4/NF-κB/TGF-β pathway." (PMID 37777746, 2023). "Pro-inflammatory cytokines TNF-α and IL-1, and CRP, can trigger the synthesis of MMPs, leading to an increase in other markers of myocardial fibrosis, and together these can activate myocardial fibroblasts." (PMID 34088886, 2021). "Inflammatory biomarkers such as C-Reactive Protein (CRP), myocardial fibrosis, and hypertrophy biomarkers such as Matrix Metalloproteinase-9 (MMP9) and soluble Suppression of Tumorigenicity 2 (sST2) have been introduced as promising biomarkers for LVR prediction." (PMID 39264503, 2025). "This means that CRP overexpression may exacerbate LV function, cardiac remodeling, and myocardial fibrosis in DCM patients, possibly through inflammation and oxidative stress." (PMID 37152931, 2023). "One recent study reported that myocardial fibrosis, elevated high-sensitivity c-reactive protein, and higher maximum modified Rodnan skin scores were independent predictors of cardiovascular outcomes in a cohort of 62 SSc patients presenting with cardiac symptoms." (PMID 31835765, 2019). "During this process, inflammatory mediators such as C-reactive protein and interleukin-6 are continuously activated, leading to myocardial cell damage, restricted myocardial energy metabolism, and inhibition of functional recovery through the induction of myocardial fibrosis." (PMID 41393266, 2025). "IL-6, frequently elevated in HF patients, stimulates hepatic synthesis of acute-phase proteins such as C-reactive protein (CRP), promotes myocardial fibrosis, and contributes significantly to ventricular hypertrophy and structural remodeling." (PMID 41154632, 2025). "The research demonstrated that the colchicine delivery system encapsulated in nanoparticles effectively reduced the levels of serum C-reactive protein (CRP), tumor necrosis Factor-alpha (TNF-α), and IL-1β, decreased the infarct area by 45%, and alleviated myocardial fibrosis." (PMID 41299461, 2025). "For example, high-sensitivity C-reactive protein (hs-CRP) mainly reflects systemic inflammatory states, while GDF-15 is involved in cellular stress responses, and JUP may be more focused on cell connection stability and myocardial fibrosis." (PMID 40433126, 2025).
pyometra (25 papers, 2007 to 2026). "Higher CRP values were expected to be reached in those with pyometra, as the underlying cause is septic, opposite to CEH." (PMID 36290272, 2022). "Detection of elevated urinary CRP has been reported before in dogs with renal disease caused by leishmaniasis, babesiosis and pyometra." (PMID 26746899, 2016). "Compared with healthy dogs, hemoglobin concentrations were higher in both septic and nonseptic dogs with pyometra (p ≤ 0.001), whereas creatinine and CRP concentrations were higher only in the septic dogs with pyometra (p ≤ 0.05 and p ≤ 0.001, respectively)." (PMID 39272157, 2024). "Further investigations are required to confirm the possible correlation between nesfatin-1 and BCS, CRP, IL-6, and the presents of ovarian cysts in bitches suffering from pyometra." (PMID 39455994, 2024). "The divergent pattern of increased serum CRP concentrations with serum ferritin concentrations within reference interval was observed in the dogs with the pyometra in both studies that we performed, indicating consistency of this finding." (PMID 37344860, 2023). "In the second study, the dynamics of CRP and ferritin in response to the surgical treatment of pyometra or elective ovariohysterectomy (OHE) of healthy bitches were evaluated." (PMID 37344860, 2023). "C-reactive protein (CRP) is arguably the most extensively researched biomarker in dogs with pyometra." (PMID 37958065, 2023). "Study 2 was performed to analyse the changes in serum CRP and ferritin in dogs with pyometra after surgical treatment." (PMID 37344860, 2023). "The magnitude of increase in CRP in dogs with pyometra compared with healthy dogs in this experiment and its dynamics of decrease after treatment was similar to a previous report in which the same procedure was made." (PMID 37344860, 2023). "After surgery, a significant increase in serum CRP occurred at D3 and D10 compared to D0 in the healthy group (P < 0.05 for both comparisons), while at D10 serum CRP decreased compared to D0 in the dogs with pyometra (P < 0.01)." (PMID 37344860, 2023). "In this report, we described a divergence in the response of two serum-positive APPs, CRP and ferritin, in canine pyometra." (PMID 37344860, 2023). "Acute-phase proteins, cytokines and chemokines have been studied, while several studies also report a correlation with plasma C-reactive protein (CRP) and pyometra." (PMID 36879277, 2023). "CRP was also investigated as a potential marker that would allow differentiating pyometra from cystic endometrial hyperplasia (CEH)." (PMID 36290272, 2022). "At present, several methods are used to diagnose canine pyometra in clinical veterinary, including uterus symptom examinations, blood routine, blood biochemical examinations, C-reactive protein (CRP), ultrasonography exam and vaginal smears." (PMID 36430638, 2022). "The highest CRP values seem to occur in dogs with severe bacterial infections, such as pyometra, with a median CRP value of 200 mg/L." (PMID 36713872, 2022). "In pyometra cases, C-reactive protein, serum amyloid A and haptoglobin concentrations can be used to monitor early post-OHE complications and ongoing inflammation." (PMID 27829462, 2016). "A time-resolved immunofluorimetic assay was used to determine the urinary CRP concentration in dogs with leishmaniasis, whereas urine samples of dogs with babesiosis and pyometra were analyzed using an ELISA-system as in the current study." (PMID 26746899, 2016). "That CRP concentrations were increased in pyometra is in accordance with findings of several other studies, and is a consequence of the severe inflammatory response induced." (PMID 25636335, 2015). "This kind of bias was avoided in most studies investigating CRP following ovariohysterectomy or pyometra." (PMID 26483038, 2015).
pyometra (continued). "Increased concentrations of CRP have previously been shown to be associated with presence of SIRS and prolonged hospitalization in bitches with pyometra, supporting the usefulness of CRP analysis in clinical practice." (PMID 25430894, 2014). "Acute phase proteins such as c-reactive protein, serum amyloid A and haptoglobin have been shown to increase in pyometra and are mainly found in the α2- and β-globulin fractions." (PMID 19134167, 2009). "Both increased CRP and PG-metabolite levels have previously been associated with presence of SIRS in canine pyometra." (PMID 17328800, 2007). "However, it is important to emphasize that a negative correlation between CRP and lipid peroxidation (TBARS) was observed in the aglepristone group, indicating the possible role of C-reactive protein as a scavenger of the oxidative stress in canine pyometra." (PMID 41463815, 2025). "Moreover, in blood parameters, an increased C-reactive protein (CRP) level is possibly the most prominent biomarker of pyometra." (PMID 39455994, 2024). "CRP levels are also elevated in dogs with pyometra and sepsis compared to those with mucometra." (PMID 37958065, 2023). "In the case of the pyometra, the presence of compatible history and clinical signs, an increase in serum CRP with serum ferritin within normal values could also be of help to suspect the presence of this disease." (PMID 37344860, 2023). "The objective of this manuscript was to study and compare the CRP and ferritin response in canine pyometra to assess whether there is a consistent divergence in their response pattern in this disease." (PMID 37344860, 2023). "This divergence response between ferritin and the other positive APPs, especially CRP, can potentially be used as an additional tool to raise the suspicion of pyometra in intact bitches when a biochemical profile of analytes including several APPs is interpreted." (PMID 37344860, 2023). "Additionally, the blood examination found an increase in inflammatory cells (white blood cells and neutrophils) and C-reactive protein, suggesting that sick dogs with pyometra suffered from systemic inflammation." (PMID 36430638, 2022). "One of the major APPs in dogs, CRP, has been shown to increase in dogs with pyometra." (PMID 25636335, 2015). "Elevated concentrations of CRP before surgery, e.g., as a result of trauma, as observed in some orthopedic patients, or infections as observed in patients suffering from pyometra, may only result in limited, additional increases post-surgery." (PMID 26483038, 2015). "CRP concentrations were significantly higher in the pyometra group compared to the control group." (PMID 25636335, 2015). "C-reactive protein has been found to be a valuable marker of SIRS in dogs with pyometra and may be of value in future studies of dogs suspected to suffer from SIRS." (PMID 18786242, 2008). "Analysis of CRP has also shown promising predictive value for severity of pyometra." (PMID 17328800, 2007). "Consequently, some researchers have proposed that CRP could serve as a marker for severe cases or be used to distinguish pyometra from mucometra." (PMID 37958065, 2023). "SPARCLTM assays have been used to quantify haptoglobin, C-reactive protein, AGP and Ceruloplasmin in the plasma of healthy dogs and dogs with pyometra." (PMID 38793672, 2024). "The main aim of this report was to investigate and compare the response of serum C-reactive protein (CRP) and ferritin, two positive acute phase proteins (APPs) which usually show an increase in inflammatory processes, in dogs with pyometra." (PMID 37344860, 2023). "Accordingly, concentrations of single APPs, such as the C-reactive protein (CRP), serum amyloid A (SAA), and haptoglobin (Hp), have been described as indicators of inflammatory response in canine pyometra." (PMID 33732740, 2021). "Significant elevation of the concentrations of CRP, SAA, and Hp were observed in dogs with pyometra." (PMID 33732740, 2021).
pyometra (continued). "CRP and SAA, which are major APPs released rapidly from the liver during the early stage of an acute phase response, increase markedly in canine pyometra." (PMID 33732740, 2021). "Similar to KC-like, the conventional biomarker CRP correlated positively with length of hospitalization, which has been shown previously, however, CRP did not discriminate between septic and nonseptic dogs with pyometra in this study." (PMID 39272157, 2024). "In both studies, bitches with pyometra showed significant increases in serum CRP, indicating an inflammatory condition, but not in serum ferritin despite being a moderate positive APP." (PMID 37344860, 2023). "In conclusion, dogs with pyometra present a divergence in the acute phase response with a major increase in serum CRP but not in serum ferritin that remains within reference intervals." (PMID 37344860, 2023). "Consistent with previous studies, the present study also revealed elevated APPs, and therefore, CRP, SAA, and Hp might be useful inflammatory indicators of canine pyometra." (PMID 33732740, 2021). "Therefore, concentrations of single APPs, such as the C-reactive protein (CRP), serum amyloid A (SAA) and haptoglobin (Hp) have been described as indicators of inflammatory response in several canine diseases, including pyometra." (PMID 33732740, 2021). "In addition, the concentration of APPs, including the C-reactive protein (CRP), serum amyloid A (SAA), and haptoglobin (Hp), were also elevated in dogs with pyometra." (PMID 33732740, 2021). "The reason for the lack of association between CgA and CRP or postoperative hospitalization (as a measurement indicator of morbidity) is unknown, and an association between CgA and mortality remains to be investigated because no dogs died of the pyometra in current study." (PMID 25636335, 2015). "NE-FSC did not correlate significantly with CRP in the pyometra group (r = 0.4430, pS = 0.050, ns)." (PMID 41301983, 2025). "However, two studies reported that CRP was not significantly different in septic and non-septic bitches with pyometra." (PMID 36879277, 2023). "CRP concentrations were not correlated with Cst or VS in the pyometra group." (PMID 25636335, 2015). "Pyometra septic: pyometra and ≥ 2 criteria fulfilled for SIRS; pyometra nonseptic: pyometra and fulfilling < 2 criteria for SIRS; HR: heart rate; RR: respiratory rate; WBC: total white blood cell count; PBN: percentage of band neutrophils; Hb: hemoglobin; CRP: C-reactive protein." (PMID 39272157, 2024).
squamous cell carcinoma (25 papers, 2013 to 2025). A carcinoma arising from squamous epithelial cells. "Two Taiwanese studies observed that a squamous cell carcinoma antigen level of 2.0 ng/ml and a CRP level of 5.0 mg/L were associated with the prognosis of OSCC and pharyngolaryngeal carcinoma." (PMID 35847918, 2022). "Upon stratification according to tumor type, a strong positive association was observed between the CRP and the mortality of patients with squamous cell carcinoma, whereas the association in patients with adenocarcinoma was relatively weak." (PMID 31148582, 2019). "The purpose of this study was to investigate an association between the prognosis for oro-hypopharynx squamous cell carcinoma treated with radiation therapy and the pre-therapeutic level of C-reactive protein (CRP)." (PMID 29259311, 2017). "Although significant associations between serum PD‐L1 levels and clinicopathological variables were observed, serum PD‐L1 level was significantly associated with high neutrophil counts, high CRP levels, low albumin levels, and high squamous cell carcinoma antigen levels." (PMID 31865635, 2020). "Therefore, this retrospective study was performed to evaluate the association between preoperative CRP levels and the incidence of nodal metastasis in patients with squamous cell carcinoma (SCC) of the penis." (PMID 24148787, 2013). "Of the four with clinically severe disease, patients 10 and 18, aged eight and six years, respectively, had the highest CRP levels, both having been operated on several times for excision of squamous cell carcinomas." (PMID 35223501, 2022). "The elevated expression levels of CRP in both adenocarcinoma and squamous cell carcinoma were observed compared with normal tissues." (PMID 31142628, 2019). "The level of IL-6 was available for eight of the squamous cell carcinoma patients during treatment and so its correlation with CRP, LRG1 and LBP was investigated during radiotherapy." (PMID 26425690, 2015). "The aim of this study was to evaluate the prognostic significance of the preoperative serum CRP level in patients with squamous cell carcinoma (SCC) of the penis." (PMID 23642165, 2013). "We cannot exclude that squamous cell carcinoma may be high proportion in the group with high dNLR and CRP." (PMID 36673123, 2023). "Univariable logistic regression analyses revealed that high PD‐L1 expression is significantly correlated with the following parameters: male sex, smoker, high SUVmax, high CRP, high KL‐6, clinical stage II‐IIIB, squamous cell carcinoma, and high fibrinogen." (PMID 39300829, 2024). "Compared to the non-ABx group, the ABx group had more patients with squamous cell carcinoma ([ABx group vs. Non-ABx group] 42.4% vs. 13.7%), tumor size of 40 mm or larger (72.7% vs. 38.1%), and elevated CRP (≥ 1.04 mg/dl) (75.8% vs. 45.2%)." (PMID 38668936, 2024). "The ROC analyses showed that the best single biomarkers for distinguishing adenocarcinoma from squamous cell carcinoma are glucose, CRP, and CYFRA 21-1; however, their combination did not significantly improve sensitivity, specificity, and the AUC value." (PMID 34439874, 2021). "Since both CRP and LRG1 were found to be significant predictive markers of survival for squamous cell carcinoma patients undergoing radiotherapy, we determined whether combining the levels of the two proteins linearly could be of value." (PMID 26425690, 2015). "At last, we could not explain why CRP substratification for adenocarcinoma was more significant than squamous cell carcinoma." (PMID 31142628, 2019).